TSPAN14 (tetraspanin 14)
Description:
Part of TspanC8 subgroup, composed of 6 members that interact with the transmembrane metalloprotease ADAM10. This interaction is required for ADAM10 exit from the endoplasmic reticulum and for enzymatic maturation and trafficking to the cell surface as well as substrate specificity. Different TspanC8/ADAM10 complexes have distinct substrates. Negatively regulates ADAM10-mediated cleavage of GP6 (By similarity). Promotes ADAM10-mediated cleavage of CDH5 (By similarity).
Synonyms: Tspan-14; TM4SF14; DC-TM4F2; MGC11352
Tractability: Antibody: UniProt places it where antibodies can reach, with high confidence; its Gene Ontology location is reachable by antibodies, with high confidence; UniProt predicts a signal peptide or a membrane-spanning region. PROTAC: ubiquitination databases record sites on it; its protein half-life has been measured.
Gene: Protein-coding gene on chromosome 10 (80,454,162 to 80,533,124, forward strand). Ensembl gene ENSG00000108219.
Subcellular location: Cell membrane
Subcellular location (Human Protein Atlas): Vesicles
Pathways (Reactome):
Immune System: Neutrophil degranulation
Metabolism of proteins: Amyloid fiber formation
Gene Ontology:
Molecular function: enzyme binding; protein binding
Biological process: positive regulation of Notch signaling pathway; protein localization to plasma membrane; protein maturation
Cellular component: plasma membrane; endoplasmic reticulum lumen; specific granule membrane; tertiary granule membrane; cell surface; membrane; tetraspanin-enriched microdomain
Genetic constraint (gnomAD): Loss-of-function variants: 15 observed, 33.72 expected, observed/expected ratio (o/e) 0.44, 90% interval 0.3 to 0.69. The upper end of that interval is the gene's LOEUF score, 0.69, which puts it in group 2 of 6, group 1 being the genes least tolerant of losing a copy. Missense variants: 220 observed, 338.16 expected, observed/expected ratio (o/e) 0.65, 90% interval 0.58 to 0.73. Synonymous variants: 134 observed, 138.16 expected, observed/expected ratio (o/e) 0.97, 90% interval 0.84 to 1.12.
Homologues: Orthologues: chimpanzee TSPAN14 (100% identical), mouse Tspan14 (97% identical), pig TSPAN14 (97% identical), rabbit TSPAN14 (97% identical), dog TSPAN14 (97% identical), rat Tspan14 (97% identical), guinea pig TSPAN14 (95% identical), macaque TSPAN14 (91% identical), tropical clawed frog tspan14 (80% identical), zebrafish tspan14 (72% identical). Paralogues in human: TSPAN17 (58% identical), TSPAN5 (58% identical), TSPAN33 (35% identical), TSPAN18 (26% identical), TSPAN11 (26% identical), TSPAN4 (25% identical), TSPAN9 (25% identical), CD151 (24% identical), CD63 (24% identical), TSPAN10 (24% identical), TSPAN15 (24% identical), TSPAN6 (24% identical), and 20 more.
Diseases named in the same sentence as TSPAN14 in open-access papers:
TSPAN14 is named in the same sentence as 20 diseases in open-access papers, as found by Europe PMC text mining. Sharing a sentence is not in itself a finding about the gene and the disease. The quoted sentences say what the papers report.
Alzheimer’s dementia (2 papers, 2021 to 2022). "As ADAM10 is implicated in several diseases, including Alzheimer’s dementia, cardiovascular diseases, and inflammation, including inflammation of the adipose tissue, it is possible that the reprogramming of TSPAN14 plays a role in cardio-metabolic health by regulating ADAM10 function." (PMID 35740266, 2022).
Alzheimer’s disease (2 papers, 2021 to 2025). A progressive, neurodegenerative disease characterized by loss of function and death of nerve cells in several areas of the brain leading to loss of cognitive function such as memory and language. "In Alzheimer’s disease (AD), we analyzed RNA-seq data from the AD Functional Genomics consortium FunGen-xQTL project and identified unproductive splicing events in 18 AD risk genes, including TSPAN14, PICALM, and CASS4, likely mediating genetic effects on disease risk." (PMID 40291686, 2025).
atherosclerosis (2 papers, 2018 to 2024). A disease characterized by the build-up of fatty material and calcium deposition in the arterial wall resulting in partial or complete occlusion of the arterial lumen. "TSPAN14 was also shown to interact with the inflammatory pathway of atherosclerosis, which has a major role in the development of CAD." (PMID 38589871, 2024). "Macrophages express relatively high levels of the Notch-promoting Tspan14, highlighting the macrophage Tspan14/ADAM10 complex as a potential therapeutic target for maintaining plaque stability in atherosclerosis." (PMID 30013551, 2018).
Obesity (2 papers, 2022 to 2024). Accumulation of substantial excess body fat. "Additionally, an adult group exposed to GDM and obesity in utero was analyzed; it was found that higher levels of HbA1c are related to an increased expression of tetraspanin 14 (TSPAN14) in subcutaneous adipose tissue." (PMID 38397953, 2024). "Based upon own previous findings in adolescent offspring of GDM women, we investigated the link between maternal diabetes and obesity in pregnancy, and the epigenetic reprogramming of ESM1, MS4A3, and TSPAN14 genes, in adult offspring blood cells and subcutaneous adipose tissue." (PMID 35740266, 2022).
Stroke (2 papers, 2022 to 2023). Sudden impairment of blood flow to a part of the brain due to occlusion or rupture of an artery to the brain. "In dataset GSE16561, with the threshold of p < 0.05, CLEC4D, GPR97, MCEMP1, and TSPAN14 were significantly upregulated in the stroke group (The platform GPL6883 did not explore FPR2's expression)." (PMID 35075378, 2022).
cerebrovascular disease (1 paper, 2022). "A previous study has reported that TSPAN14 was correlated with periventricular white matter hyperintensities which was an indicator of a history of cerebrovascular disease." (PMID 35075378, 2022).
gestational diabetes (1 paper, 2022). Carbohydrate intolerance first diagnosed during pregnancy. "Previously, we identified a lower DNA methylation degree at genomic sites near the genes ESM1, MS4A3, and TSPAN14 in the blood cells of adolescent offspring exposed to gestational diabetes and/or maternal obesity in utero." (PMID 35740266, 2022).
Hyperglycemia (1 paper, 2022). An increased concentration of glucose in the blood. "We speculate that the combination of maternal hyperglycemia and pre-gestational BMI, or pre-gestational BMI alone, regulate the gene expression changes of ESM1 and TSPAN14 in the adipose tissue of GDM offspring." (PMID 35740266, 2022). "It is noteworthy that the O-T1D group was also characterized by having leaner mothers, which suggests that other factors implicated in GDM, such as increased inflammation or lifestyle, and not mere hyperglycemia, may play a role in the epigenetic reprogramming of ESM1 and TSPAN14." (PMID 35740266, 2022).
lung adenocarcinoma (1 paper, 2023). A carcinoma that arises from the lung and is characterized by the presence of malignant glandular epithelial cells. "The TSPAN14 of key genes under the A549 cell line, is found to be a potential biomarker and provides a theoretical basis for the pathogenesis of lung adenocarcinoma." (PMID 36677903, 2023).
cancer (5 papers, 2015 to 2023). A tumor composed of atypical neoplastic, often pleomorphic cells that invade other tissues. "Our results showed that NSCLC cancer cells with the foremost potential to degrade the gelatin/matrix and migrate toward the molecular attractants had low expression of Tspan14 as well." (PMID 36143328, 2022). "What’s more, silencing the TSPAN14 in these cancer cells increased their ability to degrade gelatin, and to a limited extent, increased the migratory potential." (PMID 36143328, 2022). "Further analysis of the Tspan14 expression profile in different NSCLC cell lines confirmed decreased expression in cancer cells with higher invasive potential." (PMID 36143328, 2022). "Correspondingly, NSCLC cancer cells with the highest expression of Tspan14 had a low potential to invade and migrate through the artificial ECM models." (PMID 36143328, 2022). "Notch signaling is important in promoting many cancers, so one prediction of the Tspan5/14/ADAM10 Notch activation model is that Tspan5 and Tspan14 will promote such cancers." (PMID 34201472, 2021). "Targeting Tspan5 and/or Tspan14 has potential as an anti-Notch strategy for the treatment of Notch-driven cancers such as T-ALL and solid tumors." (PMID 34201472, 2021). "Additionally, the role of decreased TSPAN14 expression in the metastatic potential of cancer cells was confirmed in NSCLC cell lines." (PMID 36143328, 2022). "Finally, silencing of TSPAN14 in these non-metastatic cancer cells caused an increased expression of matrix-degrading enzymes MMP-2 and MMP-9, followed by an elevated capacity of cancer cells to degrade gelatin." (PMID 36143328, 2022). "It remains to be determined whether targeting Tspan5 and/or Tspan14 will provide effective Notch inhibition for certain cancers in which these proteins are over-expressed, and whether such a treatment will have lower toxicity than existing anti-Notch strategies such as γ-sectretase inhibition." (PMID 34201472, 2021).
tumor (4 papers, 2015 to 2023). "When compared to the normal lung tissue, tumor samples displayed significantly decreased TSPAN14 expression (p = 0.0005." (PMID 36143328, 2022). "Our analysis showed that the TSPAN14 gene expression level was decreased in tumor tissue derived from NSCLC patient samples." (PMID 36143328, 2022). "TSPAN14 gene expression was considered low when the expression was decreased 3-fold in the tumor compared with the matching normal tissue sample and the differences were statistically significant (p < 0.05)." (PMID 36143328, 2022). "As shown, SAV1 and TSPAN14 are more strongly stained in the tumor specimens, and there are kinds of literature showing that their expression profiles are confirmed to be related to BRCA." (PMID 34930307, 2021). "The expression level of TSPAN14 was reduced in malignant cells than in non-tumor cells." (PMID 37516981, 2023). "For instance, if we could find a way to reduce the expression of TSPAN9 or restore the expression of TSPAN14, it might help to inhibit further progression of the tumor." (PMID 37516981, 2023). "TSPAN14 expression was lower in tumor cells than non-tumor cells in NSCLC patients’ samples." (PMID 36143328, 2022). "Therefore, our data provide critical insight into the role of TSPAN14 in the pathogenesis of NSCLC, particularly when associated with processes crucial in tumor metastasis." (PMID 36143328, 2022). "Namely, TSPAN14 expression was lower in 14 of 40 tumor samples (35%)." (PMID 36143328, 2022). "The protein expression profiles of the three genes, i.e., ADRB1, SAV1 and TSPAN14, involved in the PRS model demonstrated that the latter two genes are more strongly stained in tumor specimens." (PMID 34930307, 2021). "For example, we identified several members of the tetraspanins family (Tetraspanin-14, CD9, CD63, and CD81 antigens) to be increased in tumor-derived exosomes from the non-invasive cell line, MCF-7." (PMID 25798887, 2015).
TSPAN14 also shares sentences with these, for which no sentence is quoted: breast carcinoma (1 paper); cardiovascular diseases (1); cyst (1); glaucoma (1); inflammatory bowel disease (1); non-small cell lung carcinoma (1); Parkinson disease (1); rheumatoid arthritis (1); schizophrenia (1).